CXCL1 (C-X-C motif chemokine ligand 1)
Diseases named in the same sentence as CXCL1 in open-access papers (continued):
Sharing a sentence is not in itself a finding about the gene and the disease.
infection (continued). "Infected Lum−/− corneas showed lower levels of the leukocyte chemoattractant CXCL1 by 24–48 hours of infection, and increased bacterial counts up to 5 days after infection, compared to Lum+/− mice." (PMID 23358433, 2013). "The chemokines CCL2, CCL5, CXCL1 as well as CXCL10 are all important for recruiting immune cells to the site of infection, and by inhibiting their biological activity, P. gingivalis is able to modulate and diminish the level of infiltrating immune cells." (PMID 23841502, 2013). "In the NOD-like receptor signalling pathway (hsa04621) 10 genes (of a total of 57 pathway genes) were differentially expressed at 4 h post infection and five of them were upregulated more than 10-fold, encoding IL6, IL1B, BIRC3, CXCL1 and CXCL2." (PMID 23326599, 2013). "In WT mice, levels of TNF-α, IFN-γ and CXCL-1 peaked 24 h after infection and decreased to virtually background levels after 72 h in BAL." (PMID 23991239, 2013). "CXCL1 was elevated within 24 hrs of infection in both genotypes; however, its level was consistently lower in infected Lum−/− corneas compared to Lum+/− corneas." (PMID 23358433, 2013). "A possible explanation is that Il22−/− showed a decrease in Cxcr2 expression after the peripheral infection had established (day 4 p.i.), and Il22−/− were also defective in brain Cxcl1 and Cxcl5 expression." (PMID 22952908, 2012). "The expression of CCL13, CCL19 and CXCL1 was significantly higher in cells infected with the Mtb:Δ-sigH mutant relative to Mtb or Mtb:Δ-sigH:CO at 24 hrs post-infection." (PMID 22235255, 2012). "Similar studies evaluating CXCL1 expression have shown that infection of corneal-derived cells with HSV-1 leads to significant increases in CXCL1 production, which stimulates neutrophil chemotaxis." (PMID 22593769, 2012). "The expression of several proinflammatory mediators, including IL-6, IFN-γ, and CXCL1 was significantly reduced in MyD88 KO mice, primarily at the later stages of infection." (PMID 22879997, 2012). "Twenty-four h after RV1B infection, CXCL1/KC, CXCL2/MIP-2, IL-6, CCL2/MCP-1 and IFN-γ expression in wild-type mice increased 3–5 fold." (PMID 21637773, 2011). "Four hours after infection with 105 LSE, TLR2-deficient macrophages also demonstrated diminished production of IL-6, as well as the chemokines CXCL1 and CXCL2." (PMID 20404927, 2010). "Dectin-1 mediated activation of p-Syk, p-IκB, and translocation of NFκB to the nucleus of these cells results in production of CXCL1/KC and IL-1β within 10h of infection, and recruitment of neutrophils to the corneal stroma." (PMID 20617171, 2010). "For IL-6 and CXCL1/KC, the difference was more significant at 24 h post-infection." (PMID 40818988, 2025). "We also tested whether mAb neutralization affected C. difficile colonization burden in stool and measured pro-inflammatory chemokine CXCL1/KC and cytokine IL-6 levels in blood serum and cecum/colon tissues to assess local and systemic responses to infection." (PMID 41183070, 2025). "Therefore, our findings suggest that CXCL1 is required for C5a-C5aR1 axis-mediated neuropathogenesis upon EV-A71 infection." (PMID 39679722, 2025). "Our observations revealed that CXCL1 in the brain was predominantly derived from astrocytes upon EV-A71 infection and a substantial positive correlation between the expression of CXCL1 and the activation of astrocytes in EV-A71 infection patients was observed." (PMID 39679722, 2025). "However, lower plasma levels of SCF and CXCL1 were observed in Ascaris-positive asthmatics, suggesting that previous infection with this nematode can influence plasma levels of some immune mediators." (PMID 40943268, 2025). "Lastly, exclusive expression of many genes encoding immune mediators, which allocate to signaling by interleukins or chemokines could be detected in male-derived macrophages upon infection at 6 hpi, such as CXCL1, IL32, CCL7 and IL1B." (PMID 40794782, 2025).
infection (continued). "We are not the first to show a significant increase in CXCL1 levels following pathogenic infection in Ctsz−/− mice, but to the best of our knowledge, this is the first study to directly link CTSZ and CXCL1 during TB pathogenesis." (PMID 40924769, 2025). "In addition, we recently demonstrated that KSRP attenuates the migration of PMNs toward CXCL1, the most crucial chemoattractant for PMNs in the context of infection." (PMID 39768132, 2024). "Furthermore, the observed two-fold increase of IL-8 and CXCL1 cytokine secretion upon infection in hypoxia indicates a more robust response of these cells to infection." (PMID 38720110, 2024). "However, MHV-A59 stimulated the production of CXCL1 in Smurf1−/− BMDMs as early as 12 h post-infection compared to uninfected Smurf1−/− or MHV-A59-infected wild-type BMDMs." (PMID 39452742, 2024). "ETBF infection promotes tumorigenesis via IL-17A/CXCL1 inflammatory cytokines." (PMID 39330861, 2024). "However, by 12 hours after infection, the expression of Ccl2, Cxcl1, Cxcl9, and Cxcl10 in the dLN of WT CHIKV–infected WT mice, but not MARCO–/– mice, was significantly increased in comparison with mock-infected mice." (PMID 38194268, 2024). "Various chemokines (small proteins that guide white blood cells to sites of infection, injury, or inflammation) in this pathway, such as Cxcl1, Cxcl2, Cxcl3, and Cxcl5 and Ccl20, showed significant differences in expression levels between the LV149-L and the DSS group." (PMID 39845056, 2024). "Notably, after 14 and 21 days of infection, the expression levels of CXCL1 and CCL17 significantly increased compared to the H99 infection group." (PMID 39728387, 2024). "Thus, the differential infection-related induction of Cxcl1 protein levels in the lungs and sera of K-RasLA1 mice relative to their wild-type littermates are consistent with differences in immune cell recruitment." (PMID 39338937, 2024). "Furthermore, the secretion of CXCL1 in the serum of Trim26–/–mice on day 5 post-infection was significantly higher than that in Trim26+/+ mice." (PMID 38166150, 2024). "In accordance with this, the expression of cytokines CXCL1, IL-36γ, IL-1β, and IL-6, which are thought to be critical in the recruitment of neutrophils to the infection sites and promoting inflammation, were significantly reduced in the CDI + T.mu group compared to the CDI group." (PMID 38565558, 2024). "Interestingly, our results demonstrated that interaction scores of some paired ligands and receptors (e.g., ANXA1_FPR1, CD74_APP, CD74_COPA, CXCL1_CXCR1, CXCL2_CXCR2, and HLA-F_LILRB2) were significantly increased after infection." (PMID 37087411, 2023). "CXCL1, IP-10, IL-8, lysozyme and lactoferrin were longitudinally profiled over the course of infection in a Gambian cohort study, with evidence of an inflammatory response both before, during and after detectable infection." (PMID 37862368, 2023). "While our data in infected mice suggest that inflammasome was the inflammation trigger, we show that early infection induces robust NF-κB activation that could drive the expression of chemokines such as CXCL1,9,10,11 or CCL2,3,4,5." (PMID 36851549, 2023). "CXCL1, IP-10, IL-8, lysozyme and lactoferrin were longitudinally profiled over the course of infection in a separate cohort, with evidence of an inflammatory response both before and after detectable infection." (PMID 37862368, 2023). "Upon infection, chemoattractants such as CXCL1, CXCL2 and IL-17 are produced in the lung, leading to further neutrophil recruitment and transmigration into the tissue, a process that is highly dependent on C-C chemokine receptor type 2 (CCR2)-positive blood monocytes." (PMID 37566060, 2023). "Cxcl1 and Cxcl5 production were induced in epithelial cells following chronic H. felis infection, while Cxcl2 and Cxcl3 production was induced in epithelial, myeloid, and T cell subsets following infection." (PMID 37744359, 2023).
infection (continued). "IL-6 and CXCL1 concentration were measured after 12 h of infection." (PMID 36604750, 2023). "IL-22 induced the production of CXCL1 chemokine to recruit neutrophils at the infection sites." (PMID 37403036, 2023). "IL-6, CSF 3, CXCL1, and IL-17 levels were significantly higher during infection." (PMID 37790429, 2023). "Increased expression of CXCL1 by neutrophils during ALA may support the hypothesis of inefficient initial infection control in males, leading to further excessive recruitment of neutrophils." (PMID 38179044, 2023). "At 18 hr post-infection, even though there was a higher amount of neutrophils in the airways of Ptx3−/− mice, we did not detect any differences in the levels of CXCL1 and CXCL2 between Ptx3-deficient and WT mice." (PMID 37222419, 2023). "Higher levels of Tnf, Cxcl1 and Ccl2 in Karp-infected MΦ were consistent with our in vivo results, showing the increased myeloid cell infiltration and activation in the lungs at early infection." (PMID 38091346, 2023). "CXCL1 is a potent proinflammatory mediator in inflammatory diseases and infection." (PMID 35845924, 2022). "Because we measured decreased levels of neutrophil chemokines CXCL1 and CXCL2, we hypothesized that immune cell recruitment to the lung in response to infection may be altered after fibrotic lung injury." (PMID 34990413, 2022). "In addition, corneas of mice were collected 5 days after infection to detect the RNA and protein levels of neutrophil chemokine CXCL1 and IL-1β." (PMID 35437453, 2022). "In our infection model, up-regulated Tlr-4 might have activated these pathways to eventually lead to the expressions of proinflammatory cytokiness such as CXCL1, CXCL2, etc." (PMID 36140754, 2022). "Notably, ILC3 production of LT has been described in the intestine during Citrobacter rodentium infection, and LTβR signaling in intestinal epithelial cells was required for recruitment of neutrophils to the infection site via production of CXCL1 and CXCL2." (PMID 35845169, 2022). "Importantly, Src phosphorylation and CXCL1 expression were both reduced in HAdV-D37 infection of corneas in caveolin-1 knockout mice, relative to wild-type mice." (PMID 34960773, 2021). "Although we observe reduced neutrophils in Daf-/- mice at 6 d.p.i., it is tempting to speculate that this initial reduction in CXCL1 will result in lower neutrophil recruitment later in infection." (PMID 34197564, 2021). "CXCL1 is responsible for the recruitment of neutrophils to the site of infection." (PMID 34492036, 2021). "We found that many cytokines messenger RNAs (mRNAs), including Il1b, Il5, Il6, Il10, Il12a/Il12p70, Ifng, Ccl4, Ccl5, Tnfa, Gcsf, Cxcl1, Il1a, and Il3, were significantly induced upon B.1.351 infection in the lungs of hACE2 transgenic, BALB/c, and C57BL/6 mice." (PMID 34907154, 2021). "The role of polymorphonuclear cells during in-vivo WNV infection was investigated and discussed by Bai and colleagues, who observed that macrophages quickly express high levels of Cxcl1 and Cxcl2 upon infection, leading to the recruitment of polymorphonuclear cells." (PMID 34357089, 2021). "The infection of epithelial cells has been reported to lead to the production of several cytokines, including interferons (IFNs), interleukins (IL) IL-18, IL-1, and chemokines such as KC (CXCL1) and MIP-2 (CXCL2)." (PMID 34012447, 2021). "Notably, injection of PP2 into the mouse cornea prior to infection reduced clinical signs of adenovirus keratitis and CXCL1 expression, as compared to controls." (PMID 34960773, 2021). "CXCL1 is responsible for the recruitment of neutrophils to the sites of infection." (PMID 34067003, 2021). "However, it appeared that in the DKA mouse model, the infection induced more inflammatory cytokines and chemokines involved in neutrophil (CXCL1) and macrophage (CXCL2) recruitment vs. uninfected mice and regardless of the mouse gender." (PMID 33919611, 2021).
infection (continued). "Moreover, there was a reduction in CXCL1 secretion, a key chemokine for neutrophils, after the first week of infection in infected miR-378b−/− mice." (PMID 34067003, 2021). "What’s more, either SARS-CoV-2 or it’s variants infection, Meplazumab treatment had a favorable therapeutic effect on the downregulation of cytokines and chemokines at 6 d.p.i., such as IL-6, IL10, IL1b, CCL2, CXCL1, CXCL2, IFN-γ, IL-17, and CyPA." (PMID 34564690, 2021). "Indeed, resident cells at the site of infection produce neutrophil-attracting chemokines, CXCL1 and CXCL2, following other viral infections." (PMID 34073501, 2021). "However, in response to an infection, the levels of CXCL1, RANTES, and G-CSF were significantly higher in challenged control mice." (PMID 33514747, 2021). "In addition, intestinal colonization of germ-free mice with B. longum 51A restored the ability of these mice to decrease infection by increasing the production of CXCL1 and the recruitment of neutrophils." (PMID 34557097, 2021). "Analysis of CXCL1 protein expression in lung homogenates and nasal washes showed rapid production of this chemokines within 2 h of B. pertussis challenge, which increased further over the first week of infection." (PMID 33976385, 2021). "This hypothesis is consistent with the observations that in the high-dose conidia model, IL-1R1-/- mice produced lower levels of G-CSF during infection and that CXCL1 supplementation only partially restored control of fungal growth." (PMID 34322116, 2021). "Moreover, at 24 hours after infection, CXCL1 and CXCL5 concentrations in BALF were similar in both mouse strains." (PMID 33793661, 2021). "Furthermore, non-endothelial cells, non-epithelial cells (ATII cells) and lung stromal cells were shown to be important for the induction of Cxcl1 in a MyD88/TRIF signaling dependent manner during infection with a respiratory syncytial virus (RSV)." (PMID 34737734, 2021). "The level of CXCL1 mRNA in the lungs of klotho WT mice gradually increased after infection." (PMID 33329595, 2020). "Neutrophils are recruited to the infection site by chemokines such as CXCL1 and CXCL2." (PMID 32093731, 2020). "Indeed, CXCL1 serum levels were strongly augmented in ethanol-treated mice compared to the control group at 24 hr post infection." (PMID 32701055, 2020). "Additionally, the level of CXCL1 mRNA in the lungs at 1 day post-infection was significantly higher in klotho KO mice than in klotho WT mice." (PMID 33329595, 2020). "Both CCL2 and CXCL1 were upregulated rapidly upon infection of liver tissue." (PMID 32651360, 2020). "In reference to the immunomodulatory role of LL-37, P. bovis upregulated mRNA expression of TNF-α, Cxcl-1, and IL-1β in murine phagocytic J774.A1 cells (at 2 and 8 h post-infection), whereas co-stimulation with LL-37 decreased concentrations of TNF-α, Cxcl-1, and IL-1β mRNA expression (p < 0.05)." (PMID 32117805, 2020). "Finally, in a murine epicutaneous infection model, S. aureus strongly upregulated transcripts of Cxcl1, Il6, and Il17, which required the presence of both human langerin and WTA β-GlcNAc." (PMID 31088921, 2019). "In the lungs, the levels of proinflammatory cytokines, including interleukin-1β (IL-1β) and granulocyte colony-stimulating factor (G-CSF), and of chemokines, including IP10/CXCL10, MIP1-α/CCL3, MIP1-β/CCL4, MIP2/CXCL2, and KC/CXCL1, were increased and remained high after the infection with WT cells." (PMID 30940711, 2019). "Physiologically, L. major promastigotes released during a sandfly bite may act locally to limit acute CXCL1 produced in response to the infection." (PMID 31260451, 2019). "Additionally, infection and melatonin treatment reduced the levels of KC/CXCL1 and MIP-2/CXCL2 produced by macrophages." (PMID 30949455, 2019). "CXCL1 is a critical chemokine required for neutrophil recruitment to the site of infection; thus, we propose that this metalloprotease may have evolved to evade immune responses specifically in the murine host." (PMID 31260451, 2019).
infection (continued). "In this current study, we have identified murine CXCL1 as a highly specific substrate for L. major metalloprotease and a possible immune evasion strategy employed by this parasite to establish a successful infection within the murine host." (PMID 31260451, 2019). "In conclusion, our study has uncovered a specific mechanism employed by L. major to degrade murine CXCL1 which may help the parasite to establish infection within the murine host." (PMID 31260451, 2019). "Interestingly though, the difference in the plasma levels of CXCL-1 between WT and either of the knockout mice was already seen as early as 3 h after infection." (PMID 31274379, 2019). "infection in the skin; however, the role of CXCL1 during Leishmania spp." (PMID 31260451, 2019). "However, the differences were only significant for CXCL-1 and IL-6, whereas a trend was observed throughout the entire panel of mediators released in response to infection." (PMID 31274379, 2019). "In WT mice, we found that CXCl1 (marking an M1 phenotype) was present in the brain stem by day 8 post infection, and Retnla 1 expression (marking an M2 phenotype) occurred in both the mock and 4 dpi tissues within the brain stem and sub-cortex (containing the thalamus) regions of the brain." (PMID 31415679, 2019). "GM-CSF and CXCL1 levels then decline in WT mice by day 5 post-infection." (PMID 30978245, 2019). "After 6 h of infection, the production of IL-6, CXCL1, and CCL2 increased in WT PMCs, but not in Tlr2-deficient PMCs (P < 0.001, for each at MOIs of 0.05 and 0.1)." (PMID 31636643, 2019). "Through the first four days of infection and co-treatment with eritoran, viral titers did not notably decrease; however, pro-inflammatory cytokines and chemokines, such as TNF-α, IL-1β, IL-6, and CXCL1 were mitigated during this early infection and the IAV infection resolved more rapidly." (PMID 29988424, 2018). "Also, infection with the double mutant actually suppressed the transcript levels of CXCL1 to below levels induced by the wild-type strain." (PMID 30052103, 2018). "Additionally, closer examination of the leading-edge genes of significant chemokine gene sets shows significant representation of neutrophil chemokines (Cxcl5, Ccl4 and Cxcl1), suggesting strong phase:infection interaction effect." (PMID 30134832, 2018). "In addition, no induction in TNF-α was detected in WT and PI3Kγ KO fibroblasts, while CXCL1 was induced by the infection in KO cells, although in lower levels." (PMID 29867955, 2018). "However, TLR2 was involved in expression of the pro-inflammatory cytokines IL-6 and CXCL1 by DCs following infection with S. suis and stimulation by both TLR2 ligands." (PMID 28894449, 2017). "Indeed, increased leukocyte recruitment to the brain of IFN-α/βR −/− mice was detected after 6 days of infection and was associated with elevated levels of inflammatory mediators, such as the chemokines CCL5 and CXCL1 and the cytokines IL-1β and TNF-α." (PMID 28442607, 2017). "As the overwhelming neutrophilic inflammation and intense CXCL1 and CXCL2 production seemed to be associated with the severity of IAV infection, we wondered if antagonism of the receptors for CXCL1 and CXCL2 would impact the course of infection." (PMID 29326698, 2017). "CXCL-1) were determined in mouse liver homogenates 4 days post-infection." (PMID 28536677, 2017). "Moreover, concerning CXCL1 and CXCL8 mRNA expression, it is obvious that the SM-HPBCs are more susceptible to S. aureus than the OM-HPBCs in the acute model of infection." (PMID 27446812, 2016). "The molecules that depicted significant increases in those mAb treated-mice at 96 h after infection were CXCL1 (KC), CCL2 (MCP-1), CCL3 (MIP-1α), CCL4 (MIP-1β), CXCL2 (MIP-2), CXCL5 (LIX), IL-1α, IL-6, G-CSF, M-CSF, and TNF-α (for all, P < 0.01) and IL-1β, IL-15, IL-10, and LIF (for all, P < 0.05)." (PMID 27642235, 2016). "CXCL-2 and CXCL1 are chemoattractive for neutrophils as they recruit them to the site of infection." (PMID 26974438, 2016).